MICU3 (mitochondrial calcium uptake 3)
Description:
Tissue-specific calcium sensor of the mitochondrial calcium uniporter (MCU) channel, which specifically regulates MCU channel activity in the central nervous system and skeletal muscle. Senses calcium level via its EF-hand domains: compared to MICU1 and MICU2, MICU3 has a higher affinity for calcium. MICU1 and MICU3 form a disulfide-linked heterodimer that stimulates and inhibits MCU activity, depending on the concentration of calcium. At low calcium levels, MICU1 occludes the pore of the MCU channel, preventing mitochondrial calcium uptake. At higher calcium levels, calcium-binding to MICU1 and MICU3 induces a conformational change that weakens MCU-MICU1 interactions and moves the MICU1-MICU3 heterodimer away from the pore, allowing calcium permeation through the MCU channel. The high calcium affinity of MICU3 lowers the calcium threshold necessary for calcium permeation through the MCU channel. The MICU1-MICU3 heterodimer promotes flexibility of neurotransmission in neuronal cells by enhancing mitochondrial calcium uptake in presynapses. It is also required to increase mitochondrial calcium uptake in skeletal muscle cells, thereby increasing ATP production (By similarity).
Synonyms: hMICU3; EFHA2; DKFZp313A0139
Tractability: Small molecule: a structure with a bound ligand is known. PROTAC: its protein half-life has been measured.
Gene: Protein-coding gene on chromosome 8 (17,026,877 to 17,125,880, forward strand). Ensembl gene ENSG00000155970.
Subcellular location: Mitochondrion intermembrane space; Mitochondrion inner membrane
Pathways (Reactome):
Transport of small molecules: Mitochondrial calcium ion transport; Processing of SMDT1
Gene Ontology:
Molecular function: calcium ion sensor activity; protein heterodimerization activity; calcium ion binding
Biological process: calcium import into the mitochondrion; cellular response to calcium ion; mitochondrial calcium ion homeostasis; positive regulation of neurotransmitter secretion; mitochondrial calcium ion transmembrane transport
Cellular component: mitochondrion; mitochondrial inner membrane; mitochondrial intermembrane space; uniplex complex
Genetic constraint (gnomAD): Loss-of-function variants: 14 observed, 10.34 expected, observed/expected ratio (o/e) 1.35, 90% interval 0.88 to 1.88. The synonymous counts are far from expectation, so gnomAD's model fits this gene poorly and the ratio says little. Missense variants: 341 observed, 197.97 expected, observed/expected ratio (o/e) 1.72, 90% interval 1.58 to 1.88. Synonymous variants: 156 observed, 81.84 expected, observed/expected ratio (o/e) 1.91, 90% interval 1.65 to 1.98.
Homologues: Orthologues: chimpanzee MICU3 (99% identical), macaque MICU3 (97% identical), dog MICU3 (94% identical), rabbit MICU3 (94% identical), mouse Micu3 (92% identical), rat Micu3 (91% identical), pig MICU3 (89% identical), guinea pig MICU3 (78% identical), tropical clawed frog micu3 (65% identical), zebrafish micu3b (55% identical), zebrafish micu3a (54% identical), Drosophila melanogaster MICU3 (40% identical), and 1 more. Paralogues in human: MICU2 (32% identical), MICU1 (22% identical).
Diseases named in the same sentence as MICU3 in open-access papers:
MICU3 is named in the same sentence as 13 diseases in open-access papers, as found by Europe PMC text mining. Sharing a sentence is not in itself a finding about the gene and the disease. The quoted sentences say what the papers report.
breast carcinoma (1 paper, 2025). "There is a number of scientific research for each of the top 10 mRNA genes, well-documenting their significance and association with cancerogenesis: ADAMTS5, TMEM220, ARHGAP20, MICU3; or precisely with breast cancer: COL10A1, MMP11, CAVIN2 (formerly known as SDPR), PLPP3, MME, and CD300LG." (PMID 40724805, 2025).
hemorrhagic stroke (1 paper, 2023). A stroke caused by a bleed on the brain. "This is supported by evidence that MICU3 knockdown protects the brain from damage in a rat model of hemorrhagic stroke and MICU3 deletion reduces ischemic/reperfusion injury in the heart." (PMID 37484823, 2023).
Parkinson disease (1 paper, 2020). A progressive degenerative disorder of the central nervous system characterized by loss of dopamine producing neurons in the substantia nigra and the presence of Lewy bodies in the substantia nigra and locus coeruleus. "Notably, recent GWAS studies have identified a signal in the ITPKB locus as well as the MICU3 locus as risk factors for Parkinson’s disease." (PMID 33537300, 2020).
sarcopenia (1 paper, 2022). Progressive decline in muscle mass due to aging which results in decreased functional capacity of muscles. "Restoration of MICU3 abundance in mouse muscle increased myogenesis and delayed sarcopenia." (PMID 35406743, 2022). "In mice, MICU3 abundance and MCU-dependent mitochondrial Ca2+ uptake decrease in the aging skeletal muscle leading to sarcopenia." (PMID 35406743, 2022).
cancer (3 papers, 2024 to 2025). A tumor composed of atypical neoplastic, often pleomorphic cells that invade other tissues. "Taken together, we propose that association between MICU1/MICU1, MICU2/MICU1, and MICU3/MICU1 implicated in MCU regulation shape the metabolic orientation of cancer cells." (PMID 39466877, 2024). "The correlation heatmap showed that PDE2A was positively associated with SEMA6B, RUNDC3B, MICU3, and KCNK3 genes in the majority of cancers." (PMID 39699377, 2024). "The identification of SEMA6B, RUNDC3B, MICU3, and KCNK3 as top PDE2A-correlated genes provided novel targets for functional validation studies aimed at elucidating the molecular mechanisms underlying PDE2A's role in cancer." (PMID 39699377, 2024).
tumor (3 papers, 2020 to 2025). "Genes such as AK5 and MICU3 showed expression changes in pretreatment tumor tissue, and posttreatment blood may be indicators of treatment response." (PMID 36697401, 2023). "In our risk model, the expression of five genes (PODN, NPY, MICU3, TUBB6 and RHOJ) was decreased in tumor tissues, and the greater the degree of downregulation was, the better the prognosis was, indicating that the hypermethylation of these genes may play a protective role in GC patients." (PMID 32174791, 2020).
MICU3 also shares sentences with these, for which no sentence is quoted: atherosclerosis (1 paper); cardiac hypertrophy (1); endometriosis (1); gastric cancer (1); heart failure (1); neurological disorders (1); neurotoxicity (1).